ALB (albumin)
Diseases named in the same sentence as ALB in open-access papers (continued):
Sharing a sentence is not in itself a finding about the gene and the disease.
tumor (continued). "First, albumin can impact hepatocyte catabolism through the action of proinflammatory cytokines, which are crucial in regulating tumour cell proliferation, apoptosis and invasion." (PMID 37671200, 2023). "Serum ALB level can reflect the nutritional status of the body and is related to tumor-related systemic inflammatory response." (PMID 36936656, 2023). "In this case, the tumor was significantly reduced after the treatment with albumin paclitaxel and carilizumab." (PMID 36862895, 2023). "Some of the proinflammatory cytokines available in the tumor microenvironment reduce albumin synthesis." (PMID 36511609, 2023). "This unique absorption mechanism allows albumin-based nanoparticles to overcome drug efflux mechanisms in tumor cells." (PMID 37836018, 2023). "Serum albumin exhibits a higher turnover rate within tumor tissues, which serves as an important source of energy and nutrients that support tumor growth." (PMID 37836576, 2023). "Nab-paclitaxel uses albumin associated with paclitaxel as a carrier for drug internalization in tumor cells, and its uptake is facilitated by the interaction of albumin with the cell surface receptor gp60 expressed on endothelial cells." (PMID 37046797, 2023). "Human serum albumin (HSA) based drug delivery platforms that feature desirable biocompatibility and pharmacokinetic property are rapidly developed for tumor-targeted drug delivery." (PMID 37848496, 2023). "Following similar dosimetry logistics, the tumor radiation dose of 177Lu-L1 (224 Gy) is estimated to be significantly higher than the developed albumin-based agents, considering kidney as the dose-limiting organ." (PMID 37630410, 2023). "As cancer progresses, chronic malnutrition and systemic inflammatory response against the tumor suppress hemoglobin and albumin synthesis." (PMID 36511609, 2023). "Third, the risk scoring formula consisted of three independent prognostic factors (AFP, tumor size and albumin), but their interaction effects were ignored." (PMID 37434986, 2023). "Our findings showed that EBL correlates with tumor size, duration of operation, and preoperative albumin levels." (PMID 37286991, 2023). "A novel nanoscale approach was developed for the improved cellular internalization of hybrid bovine serum albumin–lipid nanocarriers loaded with piperine (NLC-Pip–BSA) in different tumor cells." (PMID 37111611, 2023). "The increase levels of BPDE-albumin adduct and tumor biomarkers were significantly detected in the workers carrying Glu/Glu allele compared to the other two genotypes." (PMID 36287252, 2023). "In general, the half-life of human serum albumin is 3 weeks, and its preferential distribution to tumor tissue has also been reported in various articles." (PMID 37049985, 2023). "In this study, univariate analysis showed that tumor malignancy, Ki67 expression, and serum albumin levels were important influencing factors of the PFS time of the patient (P values were all < 0.05)." (PMID 38188302, 2023). "Albumin can inhibit tumor progression by stabilizing DNA replication and enhancing the immune response." (PMID 36899319, 2023). "Age, naïve or recurrence, sum of the size of the largest tumor nodule, the number of nodules, total bilirubin, albumin, AFP and DCP were significantly different." (PMID 38007597, 2023). "Albumin is an objective indicator reflecting the nutritional status of tumor patients, which can also reflect the degree of inflammation in the body to a certain extent." (PMID 37746281, 2023). "The consequence of binding to albumin and being transported to the tumor tissue has the potential to be more effective than native IL-12 at lower doses, which further decreases the risk of toxicity and results in a broader therapeutic index." (PMID 38250068, 2023). "Clinical trials revealed that UTMD combined with nab-paclitaxel, gemcitabine or technetium 99 m macroaggregated albumin had a greater prevalence of tumour response, prolonged quality of life, and extended survival." (PMID 36463323, 2023).
tumor (continued). "The fluorescence spots became more intense at 2 h post-injection, suggesting that the albumin-bound nanoparticles were specifically taken up by the tumor cells following extravasation." (PMID 36839841, 2023). "We found that tumor size, serum platelet, and serum albumin level were significantly related to RPS6K expression." (PMID 37482600, 2023). "The success of nab-PTX showed the potential of albumin as a drug carrier for imaging and tumor therapies." (PMID 37836018, 2023). "Once in vivo albumin-drug conjugate is formed, tumor specific cytotoxic payload release is required." (PMID 37049985, 2023). "They described that low tumor burden, sufficient calculated Y90 dose, increased albumin, and low ECOG score are the pre-interventional biomarkers which indicate favorable outcome." (PMID 37324012, 2023). "MAP mice were treated with PNA or albumin vehicle starting at six weeks of age, a time point at which primary tumors in cerebellum are present and small clumps of tumor cells are present in CSF, indicative of leptomeningeal disease." (PMID 37213306, 2023). "Of note, a newer rendition of FISH allows for the detection of heterogeneous mRNA expression between tumor cells and non-neoplastic cells, which has promoted the development of reliable biomarkers such as albumin mRNA for neoplasms of hepatic origin." (PMID 36826143, 2023). "For instance, nanoparticles, including membrane-camouflaged, exosome-disguised, albumin, and lactoferrin nanoparticles, are novel nanotechnologies for targeting tumor cells and regulating the tumor microenvironment in breast cancer." (PMID 36810560, 2023). "Taken together, a decrease in albumin or lymphocyte count in the peripheral blood links to tumor initiation and progression." (PMID 36662756, 2023). "Attachment of albumin‐targeting maleimide moieties led to increased tumor accumulation and anticancer activity compared to oxaliplatin." (PMID 37703130, 2023). "Confocal microscopy showed a significant increase in the penetration of menthol-modified casein nanoparticles into tumor spheroids of the C6 cell line compared with bovine serum albumin nanoparticles." (PMID 36678860, 2023). "On univariate analysis tumor stage, involvement of lymph nodes, T stage, performance status, and albumin was predictive for relapse and survival." (PMID 37232803, 2023). "ALB downregulation has been a relevant marker for liver damage, including HCC, and ALB downregulation in the tumor tissues of HCC patients has been observed in other studies at both the mRNA and protein levels." (PMID 37176094, 2023). "Albumin suppresses neutrophil extracellular trap formation in the tumor microenvironment, where neutrophils emit neutrophil extracellular traps, facilitating tumor development and metastasis." (PMID 38024341, 2023). "Albumin-based NPs synergistically facilitated the mRNA and siRNA delivery with improved anti-tumor action." (PMID 37111611, 2023). "Lastly, a nomogram was built based on age, tumor size, leucocyte,albumin(ALB), and lymphocytes/monocytes(LMR)." (PMID 36761960, 2023). "Univariate logistic regression analyses identified ECOG PS score ≥ 2, liver metastasis, tumor size ≥ 5 cm, neutrophils ≥ 69%, lymphocytes < 22%, sNLR ≥ 4, CRP ≥ 1 mg/dl, and albumin < 3.58 g/dl as significant risk factors for early death." (PMID 35871700, 2023). "We identified the 10 most important predictors, including K, low-density lipoprotein, D-dimer, red blood cell, alanine aminotransferase, albumin, monocyte, tumor size, triglyceride, and age." (PMID 36765583, 2023). "The size of albumin contributes to its accumulation in the tumor due to an enhanced permeability and retention (EPR) effect." (PMID 36985644, 2023). "Albumin-coated nanocomplexes attenuated the side effects of bufalin on weight gain in tumor-bearing mice." (PMID 36903477, 2023). "In the multivariate regression analysis, only albumin, bilirubin, tumor diameter, tumor number, and BMD remained independent prognostic factors." (PMID 35986768, 2023).
tumor (continued). "Inflammatory factors (such as interleukin‐6 and tumor necrosis factor) in the tumor microenvironment can inhibit albumin synthesis in the liver." (PMID 37434479, 2023). "We already know that prediction of 90Y-microspheres distribution in tumor and non-tumor thanks to the technetium-labeled albumin macroaggregate (99mTc -MAA) pretreatment imaging improves TARE efficacy." (PMID 37414964, 2023). "The neutrophils to albumin ratio (NAR) is predictive of mortality or has a prognostic value in several tumor types." (PMID 36766755, 2023). "Tumor-targeted delivery of bufalin-loaded modified albumin-polymer hybrids have been found to be highly effective against hepatocellular carcinoma." (PMID 36903477, 2023). "The serum albumin indicates cancer patients' nutritional status and inflammation, impacting tumor progression." (PMID 36923659, 2023). "No significant between-group differences were observed in sex, BMI, ASA scores, preoperative hemoglobin and albumin levels, tumor characteristics, or medical history, including abdominal surgery history." (PMID 37386426, 2023). "Lower albumin levels not only reflect poorer nutritional status, but also reflect tumor aggressiveness status." (PMID 36959779, 2023). "Briefly, the high AST/ALT ratio group was significantly older, had lower hemoglobin and albumin levels, higher regional lymph node and distant metastasis rates, greater rate of high tumor volume, and shorter TTCR." (PMID 37714917, 2023). "Albumin has the highest concentration of plasma proteins in the body and, due to its high solubility, it is an excellent drug carrier for tumor cells." (PMID 37909596, 2023). "The binding ability of the gp60, gp30, gp18, and FcRn receptors to albumin ensures the transcytosis of albumin-based nanoparticles within the tumor cells." (PMID 37836018, 2023). "When conjugated with the p32-binding LyP-1 peptide (CGQKRTRGC), Abraxane, a nanoparticle albumin-bound paclitaxel, accumulated in tumor tissues and inhibited tumor growth more efficiently than untargeted Abraxane19,20." (PMID 37258584, 2023). "Albumin can contribute to enhance tumor specificity, reduce drug induced cytotoxicity and retain concentration of the therapeutically active agent such as drug, peptide, protein, and gene for a prolonged time duration." (PMID 37828259, 2023). "We and others have reported that bispecific nanobody derivatives simultaneously targeting tumor antigens and albumin have improved biodistribution profiles and can serve as vectors for developing the theranostic toolbox." (PMID 36939440, 2023). "These two groups of patients were well balanced in terms of age, sex, ASA score, BMI, gastrectomy, tumor grade, pathological N staging, perineural invasion, tumor size, preoperative albumin level and preoperative hemoglobin level." (PMID 37007142, 2023). "PNI is a composite index that can reflect the nutritional status and immune status at the same time based on serum albumin level and peripheral blood lymphocyte count, which is mostly used for the prognosis of postoperative surgery or tumor patients." (PMID 37005959, 2023). "Albumin synthesis decreases in response to the production of some inflammatory factors involved in tumor immunity and the acute phase response, such as tumor necrosis factor, interleukin-6, and C-reactive protein (CRP)." (PMID 37576904, 2023). "Systemic immune-inflammation index–albumin-bilirubin 2 category was associated with relatively higher AFP levels, bigger largest tumor size, more BCLC C stage, and worse OS." (PMID 36620927, 2023). "The combined treatment of albumin paclitaxel and carrelizumab (anti-PD-1 immunotherapy) was effective in reducing the tumor, but it increased the severity of the skin ulceration." (PMID 36862895, 2023). "Placing a magnetic field outside the tumor site can make the drug-loaded magnetic albumin nanoparticles focus on tumor site." (PMID 37091158, 2023).
tumor (continued). "Our results demonstrated that the active process of endothelial transcytosis is the dominant pathway for albumin-bound nanoparticles’ entry into tumor." (PMID 36839841, 2023). "The 18 feature variables were N-stage, SIRI, age, FIB, LMR, T-stage, N, positive lymph nodes, histologic grade, HCY, Na, WBC, albumin, L, tumor size, OTSCC classification, PLR, and SG." (PMID 37574562, 2023). "Because albumin preferentially accumulates at the tumor tissue, the clinically available heptamethine cyanine dye ICG has been successfully used for NIR fluorescence-guided tumor diagnosis and phototherapy after combining with HSA or BSA." (PMID 36614318, 2023). "As shown, significant differences in several baseline variables were observed, including tumor size, MoRAL scores, platelet counts, aspartate aminotransferase levels, alanine aminotransferase levels, prothrombin time, and albumin before IPTW." (PMID 36925930, 2023). "By multivariate analysis, we identified naïve/recurrence, number of nodules, size of the largest tumor, total bilirubin, albumin and AFP levels as independent predictors of overall survival in intermediate stage HCC patients." (PMID 38007597, 2023). "In the case of 5-MTHF-based radioconjugates modified with the 4-(p-iodophenyl)butanoate-based albumin binder, the increase in tumor uptake was even more pronounced for [177Lu]Lu-6S-RedFol-1 and [177Lu]Lu-6R-RedFol-1 compared with [177Lu]Lu-OxFol-1." (PMID 37686538, 2023). "This increased uptake possibly occurs via specific albumin (albondin) receptors, so that albumin-functionalized nanoparticles are taken up by tumor cells to a greater extent than by normal cells, thus exerting their cytotoxic effects on cancer cells." (PMID 37514119, 2023). "Multiple regression analysis showed age, naïve or recurrence, the size of the largest tumor nodule, the number of nodules, total bilirubin, albumin and α-fetoprotein as independent predictors of survival." (PMID 38007597, 2023). "Multiple nutritional assessment systems, including Nutritional Risk Screening (NRS), albumin (ALB), and prognostic nutritional index (PNI), have been shown to predict the prognosis of tumor patients." (PMID 37853186, 2023). "The data in this study demonstrated that in combination with the 5-MTHF-based FR-targeting entities, a reasonably high tumor uptake can also be achieved with weaker albumin binders (diastereoisomers of [177Lu]Lu-RedFol-24 and [177Lu]Lu-RedFol-25)." (PMID 37686538, 2023). "Although researchers have reported good tumor targeting with such a short blood half-life, others have worked to extend the half-life of Nbs, for example by fusing the Nb to albumin, to prevent such rapid clearance and allow for maximal tumor uptake." (PMID 37444603, 2023). "The ranking of albumin, a primary tumor on the colon’s right side, and sizes and multiplicity of the colorectal liver metastases varied." (PMID 38004052, 2023). "There are differences in the way that albumin-based hydrogels are applied for the treatment of different types of tumor." (PMID 37113668, 2023). "This receptor is found on tumor endothelial cell surfaces, and after the interaction with albumin, it binds to the caveolin-1 protein." (PMID 37836018, 2023). "Changing to possible nanobiocarriers of boron agents, serum albumin has demonstrated significant results on tumor delivery and therapeutic effect." (PMID 37627119, 2023). "The cell membrane is invaginated to form transport vesicles, so albumin carriers accumulate in the tumor to achieve targeted drug delivery." (PMID 37177365, 2023). "Statistically significant differences were observed in factors such as age, CEA, WBC count, albumin level, time of GC surgery, tumor size, postoperative metastasis, nerve invasion, and the interval from gastrectomy to first SBO (p < 0.05)." (PMID 37946228, 2023).
tumor (continued). "The RDA/CAA environmental factor analysis showed that the cancer antigen CA199 had the greatest effect on tumor tissue bacteria, followed by albumin and leukocytes." (PMID 36563106, 2023). "Conjugating an albumin-binder is a common strategy for the design of radiotherapeutic ligands to extend their blood residence time and to enhance overall tumor uptake." (PMID 37649602, 2023). "Development of the second-generation anti-HER2 Affibody molecule ABY-027 for radionuclide therapy added advantages of a more stable tumor-seeking domain, higher affinity to albumin, and site-specific conjugation of the radionuclide." (PMID 37173878, 2023). "TPEF has also been used in fluorescence lifetime imaging microscopy to identify a gradient of human serum albumin (HSA) from normal connective tissue to the tumor tissue, with HSA being labelled with the two-photon probe squaraine (SD)." (PMID 36901838, 2023). "The albumin is a promising carrier for targeted tumor imaging and drug delivery because it can be selectively accumulated inside the tumor interstitium, known as the enhanced permeation and retention (EPR) effect." (PMID 36614318, 2023). "In another study, researchers investigated the cascade two-stage tumor re-oxygenation and immune re-sensitization mediated by self-assembled albumin-sorafenib NPs for enhanced photodynamic immunotherapy." (PMID 37047123, 2023). "HUVECs were co‐cultured in transwell inserts in the presence of tumour cells for 96 h, and then Evans blue‐albumin was measured through the endothelial monolayer for 90 min." (PMID 37132170, 2023). "Multiple linear regression analysis was conducted with gender, age, BMI, tumor type, tumor stage, ALB, PAB, Hb, TLC, TRF, diet, the NRS2002 score, acute toxicity level, and chemotherapy as independent variables." (PMID 37599990, 2023). "Manganese in the form of NPs, more specifically albumin-coated manganese dioxide (MnO2) NPs, have been able to subdue tumor hypoxia and enhance radiotherapy." (PMID 37593220, 2023). "Similar results were found when Cy5.5 was conjugated on albumin, where tumor targeting was improved but background uptake was also increased." (PMID 38203730, 2023). "These authors engineered a nano formulation consisting of human serum albumin possessing the LRP-1-binding peptide and B5 for tumor targeting, along with 5-FU and Cy7 (Cy7–B5–HSA–5-FU)." (PMID 36980778, 2023). "These novel nanoparticle albumin-bound drugs will hopefully display higher tumor penetration and anti-tumor activity in various cancers, including GI cancers." (PMID 37509639, 2023). "The most significant feature of cRGD-MID-AC is the high retention of cellular boron concentration owing to the tumor accumulation mechanism of albumin as well as MID-AC." (PMID 36979069, 2023). "Since our method can distinguish the origin of the albumin, it is able to provide new insight into tumor-dependent packaging of albumin into EVs." (PMID 36470535, 2023). "In vivo, albumin camouflage in Fe3O4@MIPs led to a 2.6-fold improvement in tumor accumulation in comparison to Fe3O4@NIPs, and more heat was produced upon 808 nm laser irradiation, which further triggered efficient immunogenic cell death." (PMID 37173721, 2023). "Meanwhile, the level of serum albumin in HCC is also closely related to the parameters of tumor number, tumor size, and portal vein invasion." (PMID 36675418, 2023). "All patient received 2 to 3 cycles of albumin-bound paclitaxel combined with nedaplatin before surgery, tumor regression grade (TRG) and American National Cancer Institute Common Toxicity Criteria version 5.0 were used to evaluate its efficacy and safety." (PMID 36862884, 2023). "Rather, it circulates in the blood, conjugated to albumin, and accumulates selectively in tumor cells via lysosome endocytosis, relying on increased vascular permeability at the blood–tumor barrier." (PMID 37568734, 2023).